GNA14 (G protein subunit alpha 14)
Description:
Guanine nucleotide-binding proteins (G proteins) are involved as modulators or transducers in various transmembrane signaling systems.
Synonyms: HG1I
Tractability: Antibody: its Gene Ontology location is reachable by antibodies, with high confidence. PROTAC: ubiquitination databases record sites on it.
Gene: Protein-coding gene on chromosome 9 (77,423,079 to 77,648,322, reverse strand). Ensembl gene ENSG00000156049.
Pathways (Reactome):
Hemostasis: ADP signalling through P2Y purinoceptor 1; Thrombin signalling through proteinase activated receptors (PARs); Thromboxane signalling through TP receptor
Signal Transduction: G alpha (q) signalling events; G-protein activation; PLC beta mediated events
Metabolism: Acetylcholine regulates insulin secretion; Fatty Acids bound to GPR40 (FFAR1) regulate insulin secretion
Metabolism of proteins: Cooperation of PDCL (PhLP1) and TRiC/CCT in G-protein beta folding
Gene Ontology:
Molecular function: protein binding; G protein activity; G protein-coupled receptor binding; G-protein beta/gamma-subunit complex binding; GTP binding; GTPase activity; guanyl nucleotide binding
Biological process: cell chemotaxis; phospholipase C-activating G protein-coupled receptor signaling pathway; positive regulation of inflammatory response; action potential; adenylate cyclase-modulating G protein-coupled receptor signaling pathway; phospholipase C-activating dopamine receptor signaling pathway; signal transduction; G protein-coupled receptor signaling pathway
Cellular component: extracellular exosome; heterotrimeric G-protein complex; plasma membrane
Genetic constraint (gnomAD): Loss-of-function variants: 36 observed, 31.44 expected, observed/expected ratio (o/e) 1.14, 90% interval 0.88 to 1.51. The upper end of that interval is the gene's LOEUF score, 1.51, which puts it in group 6 of 6, group 1 being the genes least tolerant of losing a copy. Missense variants: 330 observed, 325.72 expected, observed/expected ratio (o/e) 1.01, 90% interval 0.93 to 1.11. Synonymous variants: 114 observed, 120.7 expected, observed/expected ratio (o/e) 0.94, 90% interval 0.81 to 1.1.
Homologues: Orthologues: chimpanzee GNA14 (99% identical), macaque GNA14 (99% identical), pig GNA14 (98% identical), dog GNA14 (97% identical), rat Gna14 (97% identical), guinea pig GNA14 (97% identical), mouse Gna14 (97% identical), rabbit GNA14 (96% identical), tropical clawed frog gna14 (90% identical), zebrafish gna14a (75% identical), Drosophila melanogaster CG30054 (63% identical), Drosophila melanogaster CG17760 (60% identical), and 16 more. Paralogues in human: GNA11 (82% identical), GNAQ (81% identical), GNA15 (56% identical), GNAI1 (53% identical), GNAI3 (52% identical), GNAO1 (52% identical), GNAI2 (51% identical), GNAT2 (50% identical), GNAT3 (50% identical), GNAT1 (50% identical), GNAZ (48% identical), GNA13 (47% identical), and 3 more.
Diseases named in the same sentence as GNA14 in open-access papers:
GNA14 is named in the same sentence as 46 diseases in open-access papers, as found by Europe PMC text mining. Sharing a sentence is not in itself a finding about the gene and the disease. The quoted sentences say what the papers report.
hemangioma (5 papers, 2021 to 2025). A benign vascular lesion characterized by the formation of capillary-sized or cavernous vascular channels. "These outcomes provided solid evidence that cherry hemangiomas should be classified as benign vascular neoplasms caused most commonly by a mutation in the GNA14 gene." (PMID 39518110, 2024). "The frequency of GNA gene mutations (GNAQ, GNA11 and GNA14) was highest with more than 52% in cases diagnosed as cherry (or senile) hemangioma." (PMID 34040639, 2021). "In line with two recently published cohorts of 85 hemangiomas, we also found GNA14 and GNAQ alterations to be the most common mutations in our cohort of benign vascular tumors." (PMID 34040639, 2021). "For hemangioma and vascular malformations, patients with GNA14 mutations (n = 9) and GNAQ (n = 5) tended to be younger than the average cohort." (PMID 34040639, 2021). "GNAQ, GNA11, and GNA14 (particularly GNA14 Q205L) mutations, which were mutually exclusive, were identified in approximately half of the cherry hemangiomas and cherry hemangioma-like hemangiomas." (PMID 39518110, 2024). "The results of these studies implicate that the essential mechanism underlying the pathogenesis of anastomosing hemangioma is related to GNAQ mutations, as well as its paralogues: GNA11 and GNA14." (PMID 39518110, 2024). "For cherry, congenital, anastomosing hemangioma, GNA14, GNA11 and GNAQ alterations have been described to be the most common alterations in these subtypes." (PMID 34040639, 2021). "Our study identifies GNA14 Q205, GNA11 and GNAQ Q209 mutations as being the most common and mutually exclusive mutations in benign hemangiomas." (PMID 34040639, 2021). "A potential driving mechanism is that constitutive GTPase activity and the mitogen-activated protein (MAP) kinase signaling pathway are regulated by the recurrent mutant G protein alpha subunit GNAQ and its paralogs GNA11 and GNA14, which are also expressed in other hemangiomas." (PMID 40416971, 2025). "Our findings demonstrate that GNA gene (GNAQ, GNA11, GNA14) mutations are a major pathogenetic event in benign vascular proliferations, however, primarily in hemangioma and not vascular malformations." (PMID 34040639, 2021). "GNA14 mutations have not been reported in melanocytic tumors, but were the most frequent mutations observed in our cohort of benign hemangioma and vascular malformations (n = 9)." (PMID 34040639, 2021). "Recent studies have reported the presence of mutually exclusive mutations in GNA14 Q205, GNA11, and GNAQ Q209 in benign hemangiomas, but not in malignant vascular tumors, which supports the histologic impression of THOA." (PMID 39360118, 2024).
hepatocellular carcinoma (5 papers, 2021 to 2025). A malignant tumor that arises from hepatocytes. "The downregulation of GNA14 in hepatocellular carcinoma is significantly associated with tumor grade, clinical stage, and T stage." (PMID 37405532, 2024). "GNA14, encoding a member of the guanine nucleotide binding, or G protein family, was a well-known target in hepatocellular carcinoma and vascular tumors." (PMID 37251921, 2023). "Besides GLS, two additional genes incorporated into the prognostic model- GNA14 and GNG4-may also contribute to hepatocellular carcinoma biology." (PMID 41348762, 2025).
vascular tumors (4 papers, 2018 to 2023). "Moreover, activating mutations in GNA14 have been found in various vascular tumors and hepatic small vessel neoplasm, and research has revealed higher expression of GNA14 in endometrial carcinoma tissues than in hyperplasia tissues." (PMID 37760541, 2023). "Recently, somatic mutations in GNA14 have been linked to congenital and sporadic vascular tumors." (PMID 29770609, 2018). "A study found that GNA14 mutations could cause vascular tumors in children." (PMID 32337286, 2020).
endometrial carcinoma (3 papers, 2021 to 2024). A malignant tumor arising from the epithelium that lines the cavity of the uterine body. "Previous study has shown that silencing of GNA14 inhibits endometrial cancer cells’ proliferation by inducing apoptosis and G2/M cell cycle arrest." (PMID 37760541, 2023).
Hypertension (3 papers, 2012 to 2023). The presence of chronic increased pressure in the systemic arterial system. "The protein encoded by GNA14 was involved in the regulation of insulin secretion pathway, and the relationship of insulin, insulin sensitivity, and hypertension had been clearly confirmed." (PMID 36869404, 2023). "We also see three genes implicated in hypertension: Wisp1, Gna14, and F11r." (PMID 22471599, 2012).
colon cancer (2 papers, 2016 to 2023). "These two cells do not show any unique molecular features that make them different from other colon cancer cell lines with respect to GNA14 expression, but they do share the commonality of being colon-like cell lines." (PMID 37760541, 2023). "In this study, we analyzed the biological function of GNA14 in colon cancer using the GNA14 knockdown method in CRC cells and by crossing Gna14 knockout mice with ApcMin mice, a representative mouse model of CRC." (PMID 37760541, 2023). "Three regions: 3p14.2 (deletion), 9p21.2q21.31 (amplification), and 20q13.12 (amplification) were commonly found in HN4 and HN31 as the same cluster in our analysis, and five genes (FHIT, MMP9, GNA14, GNAQ, and PSAT1) were involved in tumorigenesis in lung cancer and colon cancer." (PMID 27501229, 2016).
colorectal cancer (2 papers, 2023 to 2024). A primary or metastatic malignant neoplasm that affects the colon or rectum. "In addition, previous research has reported that 2.7% of colorectal cancers have somatic mutations in GNA14." (PMID 37760541, 2023). "To investigate the role of GNA14 in colorectal cancer, we first examined GNA14 gene expression in several CRC cells." (PMID 37760541, 2023). "GNA14 might accelerate colorectal cancer cell proliferation and malignant tumor progression through ERK and β-catenin pathways." (PMID 39497824, 2024). "Analysis of GEO datasets using GEO2R has shown that while Gna14 is one of the genes whose expression increases during progression from adenoma to carcinoma in ApcMin mice, the role of GNA14 in colorectal cancer remains unknown." (PMID 37760541, 2023). "To determine the cause of decreased cell proliferation due to GNA14 knockdown, we investigated potential changes in the MAPK and AKT pathways, two of the most important signaling pathways involved in the proliferation and survival of colorectal cancer cells." (PMID 37760541, 2023).
liver cancer (2 papers, 2021 to 2024). An epithelial or non-epithelial malignant neoplasm that arises from the liver. "Subsequent experiments have confirmed the discovery that GNA14 is a prognostic protective gene in patients with liver cancer." (PMID 37405532, 2024). "As a result, the growth of the subcutaneous human liver cancer xenograft in nude mice of the GNA14 overexpression group was inhibited." (PMID 33500727, 2021). "In the TCGA database, there was a hypermethylation state in the promoter region of the GNA14 gene in liver cancer tissues." (PMID 33500727, 2021).
thyroid cancer (2 papers, 2020 to 2024). "Among the top 30 hub genes obtained in PPI network, the expression levels of FN1, NMU, CHRDL1, GNAI1, ITGA2, GNA14 and AVPR1A were associated with the prognosis of thyroid cancer." (PMID 32337286, 2020). "The Human Protein Atlas (HPA)-based Immunohistochemistry (IHC) database showed that FN1, NMU, and ITGA2 were upregulated in thyroid cancer tissues compared with normal tissues, while CHRDL1, GNAI1 and GNA14 were downregulated in thyroid cancer tissues." (PMID 32337286, 2020). "Using data mining based on bioinformatics tools, the present study has confirmed CHRDL1, GNAI1, GNA14 and AVPR1A are associated with thyroid cancer although their specific biological functions have not been explored by the molecular biology methods." (PMID 32337286, 2020). "Hence, we derived seven key genes related to the prognosis of thyroid cancer: FN1, NMU, CHRDL1, GNAI1, ITGA2, GNA14, AVPR1A." (PMID 32337286, 2020).
adenoma (1 paper, 2023). A neoplasm arising from the epithelium. "Adenoma grades in control and Gna14 knockout mice were classified into low-grade adenoma, high-grade adenoma, and adenocarcinoma." (PMID 37760541, 2023). "Meanwhile, both immunostaining of phospho-ERK in adenomas of the distal small intestine and immunostaining of phospho-β-catenin at S675 in the nucleus were reduced in Gna14 knockout mice compared to controls." (PMID 37760541, 2023).
Alzheimer disease (1 paper, 2018). A progressive, neurodegenerative disease characterized by loss of function and death of nerve cells in several areas of the brain leading to loss of cognitive function such as memory and language. "GNA14 appears to play a key role in the genetic architecture underlying normal gray matter density and a GNA14 deletion mutation has been reported in a patient with early‐onset Alzheimer disease." (PMID 29770609, 2018).
angiosarcoma (1 paper, 2021). A malignant tumor arising from the endothelial cells of the blood vessels. "In our cohort of angiosarcomas no alterations in GNA14 or GNA11 were identified." (PMID 34040639, 2021).
benign vascular tumor (1 paper, 2021). "Frequent activating hotspot mutations in GNA genes, including GNA14 Q205, GNA11 and GNAQ Q209 were identified in 16 of 64 benign vascular tumors (25%)." (PMID 34040639, 2021).
blepharospasm (1 paper, 2019). "Interestingly, a recent study showed that deleterious variants in CACNA1A, REEP4, TOR2A, ATP2A3, HS1BP3, GNA14, and DNAH17 were involved in blepharospasm, and none of these variants except for CACNA1A has been reported to be associated with blepharospasm." (PMID 32038460, 2019).
cervical dystonia (1 paper, 2018). "Deleterious variants in HS1BP3 (NM_022460.3: c.94C>A, p.Gly32Cys) and GNA14 (NM_004297.3: c.989_990del, p.Thr330ArgfsTer67) were identified in a father and son with segmental cranio‐cervical dystonia first manifest as BSP." (PMID 29770609, 2018).
Dystonia (1 paper, 2018). An abnormally increased muscular tone that causes fixed abnormal postures. "A small pedigree with BSP+ and Parkinsonism harboring variants in HS1BP3 and GNA14 highlights the distinct possibility of oligogenic inheritance in BSP and other anatomical distributions of dystonia." (PMID 29770609, 2018).
head and neck cancer (1 paper, 2024). A primary or metastatic malignant neoplasm affecting the head and neck. "For example, in head and neck cancers, we found significant correlation of higher survival and higher expression of the SSTR2-SST, RXFP3-INSL5, and RXFP1-RLN3 signaling axis, which all share similar coupling profiles (e.g., Gq/11, particularly GNA14, as well as Gi/o)." (PMID 38723607, 2024).
kaposiform hemangioendothelioma (1 paper, 2023). Kaposiform hemangioendothelioma is a very rare, aggressive, vascular tumor manifesting in the neonatal period or in infancy as cutaneous vascular tumors to large infiltrative lesions. "Lymphatic malformations (LMs) are associated with mutations of the PIK3CA (phosphatidylinositol-4,5-bisphosphate 3-kinase catalytic alpha subunit) gene, while Kaposiform Hemangioendothelioma (KHE) is associated with the GNA14 (G protein alpha subunit 14) mutation." (PMID 38201347, 2023).
lymphatic malformation (1 paper, 2023). Primary lymphedema is caused by anatomic or functional defects in the lymphatic system, resulting in chronic swelling of body parts and lymphatic-system malformation. "The identification of specific genetic mutations associated with certain types of malformations and lesions, such as PIK3CA mutations in lymphatic malformations and GNA14 mutations in Kaposiform Haemangioendothelioma, has opened doors for targeted therapies using pathway inhibitors." (PMID 38201347, 2023).
melanoma (1 paper, 2025). A malignant, usually aggressive tumor composed of atypical, neoplastic melanocytes. "Thus, for the first time, we identified a change in FGF/FGFR versus GNA14/Th1 signaling as the major underlying signaling context of filaggrinHigh melanomas, which can be further explored through clinical and experimental studies." (PMID 40765578, 2025). "Based on GSEA, network analysis, and Enrichr profiling, we identified for the first time that upregulated FGF/FGFR, allergic signatures versus impaired GNA14, and Th1 signatures as the major changes in the context of filaggrinHigh melanomas." (PMID 40765578, 2025). "We identified that the major signaling context changes behind filaggrinHigh melanomas are active FGFR signaling and impaired GNA14 and Th1 signatures, in addition to many genetic and immune changes that are associated with pruritus." (PMID 40765578, 2025).
nasopharyngeal carcinoma (1 paper, 2024). A carcinoma arising from the nasopharyngeal epithelium. "In addition, we found that patients with low GNA14 expression were less sensitive to chemotherapeutic agents such as 5-fluorouracil and gemcitabine, which are commonly used chemotherapeutic agents in nasopharyngeal carcinoma, suggesting that these patients may have poorer response to chemotherapy." (PMID 39659788, 2024).
polyp (1 paper, 2023). A usually exophytic mass attached to the underlying tissue by a broad base or a thin stalk. "Because the number and size of polyps between control and Gna14 knockout mice differed significantly in the distal small intestine, polyp grade was assessed using histopathological analysis of the distal small intestine." (PMID 37760541, 2023).
uterine corpus endometrioid carcinoma (1 paper, 2025). "One study found that G protein alpha subunit 14 (GNA14) promoted uterine corpus endometrioid carcinoma development." (PMID 40661182, 2025).